Y_RNA (Y RNA )
Gene: Miscellaneous RNA gene on chromosome 7 (151,916,331 to 151,916,418, forward strand). Ensembl gene ENSG00000222941.
Homologues: Orthologues: chimpanzee Y_RNA (98% identical), chimpanzee Y_RNA (97% identical). Paralogues in human: Y_RNA (86% identical), Y_RNA (85% identical), RNY4 (83% identical), Y_RNA (83% identical), RNY4P10 (81% identical), Y_RNA (81% identical), RNY4P6 (80% identical), Y_RNA (80% identical), RNY4P14 (78% identical), RNY4P34 (78% identical), RNY4P36 (78% identical), RNY4P7 (78% identical), and 87 more.